Y_RNA (Y RNA )
Gene: Miscellaneous RNA gene on chromosome 10 (72,220,752 to 72,220,852, forward strand). Ensembl gene ENSG00000200170.
Homologues: Orthologues: chimpanzee Y_RNA (98% identical), macaque Y_RNA (91% identical). Paralogues in human: Y_RNA (89% identical), Y_RNA (87% identical), RNY3 (86% identical), RNY3P16 (86% identical), Y_RNA (86% identical), RNY3P1 (85% identical), Y_RNA (85% identical), Y_RNA (84% identical), RNY3P14 (83% identical), RNY3P7 (83% identical), Y_RNA (83% identical), Y_RNA (82% identical), and 95 more.